CD4 (CD4 molecule)
Diseases named in the same sentence as CD4 in open-access papers (continued):
Sharing a sentence is not in itself a finding about the gene and the disease.
infection (continued). "This may have particular relevance given the potential role of mucosal antigen-presenting cells in the uptake and subsequent presentation of HIV-1 to CD4+ target cells (18, –, 21), facilitating dissemination through cis- and trans-infection pathways." (PMID 27795431, 2017). "For this, CD4+ T cells were sorted from infected WT mice to high purity levels and were then transferred to both Il18r1−/− and Myd88−/− mice, 20 hr before infection." (PMID 28895840, 2017). "Because CB17 SCID mice develop severe liver necrosis upon R. typhi infection, we also assessed serum GPT levels as a measure for liver damage in all groups of mice at the time of death and in surviving CD4+IFNγ-/- T cell recipients at day 34 post infection when the experiment was terminated." (PMID 28222146, 2017). "More recently, a murine study has definitively classified the CD4 T-cell population as anergic; anergy could be induced by both live infection and injection of a tegumental antigen preparation (FHTEG)." (PMID 28871261, 2017). "Conversely, in a secondary infection, the recruitment of pre-existing circulating effector CD4+ Th1 cells leads to the rapid control of the parasites, and CD4+ TRM cells contribute by promoting the recruitment of these effector T cells to the site of infection." (PMID 28419151, 2017). "Similarly, broadly reactive CD4 T cells are predominantly detectable during acute infection, whereas their numbers decline during chronic infection." (PMID 28862649, 2017). "However, up until this point, the contribution of cytokine-producing B cells in the context of inflammation, infection, and autoimmunity, which were conventionally dependent on CD4+ T cells, was an unexplored aspect." (PMID 29176972, 2017). "Of note, the depletion of CD4+ T cells in WT mice did not abrogate the infection-induced changes in weight, suggesting that the CD4+ T cells in WT mice are not pathogenic." (PMID 28129374, 2017). "As reported MTB infection is associated with an increase in the frequency of CD4+CD25+FoxP3+Treg in the blood and at the site of infection, resulting in MTB specific immunity suppression that may foster the chronicity of MTB infection." (PMID 29259310, 2017). "infection via IL-4-induced differentiation of naive CD4+ T cells into TH2 cells." (PMID 29295550, 2017). "To evaluate whether S. Typhimurium infection induces the differentiation of Treg cells in these tissues, C57BL6 mice we orally infected with 1 × 105 CFUs and 96 h post-infection were measured the amount of CD4+CD25+FoxP3+ and CD4+CD25+FoxP3− T cells in situ." (PMID 28824622, 2017). "However, very early in infection, before numerical CD4 T-cell loss, HIV causes defects in CD4 T-cell and MHC-II antigen-presenting cell (APC) function, defects which also affect B-cell responses to infection." (PMID 28701402, 2017). "We did not observe an association between markers of recent infection, either high CD4 count or a low avidity index, and prevalence of TDRMs." (PMID 27476929, 2017). "Finally, sustained IFN-I expression during LCMVCL13 infection also suppresses de novo Th1 differentiation in late primed virus-specific CD4." (PMID 29301196, 2017). "Microbial exposure significantly enhanced both HIV-1 CH040.c infection and CD4+ T cell killing." (PMID 28241075, 2017). "However, the existence of chronic or intermittent low-level viral replication replenishes the viral reservoir by infection of additional CD4 T cells, some of which become latently infected resting memory CD4 T cells." (PMID 29182633, 2017). "Also at the time of first pVL, only a small number of patients had CD4>750 cells/mm3 (i.e., indicative of recent infection) and their viral load was ≥2.78 log10 copies/mL." (PMID 28152073, 2017).
infection (continued). "In the entire EU/EEA, 120,100 (95% confidence interval (CI): 113,000–127,800) people were estimated to be living with undiagnosed HIV by the end of 2015, of whom 47% had a CD4 count ≥500 cells/mm3 and 31% <350 cells/mm3, with 28,000 (95% CI: 24,700–31,700) new infections in 2015." (PMID 28953320, 2017). "No definitive HIV outgrowth could be detected with a qVOA performed 32 months after infection utilizing 20 million input total CD4+ T cells." (PMID 29112956, 2017). "In this work, we used a phosphoproteomic approach and a secondary siRNA screen to characterize signaling induced by HIV‐1 upon entry to immature monocyte‐derived DCs and identify those signaling molecules required for trans‐infection of autologous CD4+ T cells." (PMID 28923824, 2017). "For men with infection attributed to male-to-male sexual contact, estimates based on data adjusted for reporting delays from the CD4 (EAPC −1.0%, 95% CI −2.2% to 0.3%) and the Bayesian hierarchical models (EAPC 0.66%, 95% CI 0.31%-1.01%) no longer indicated a decrease in incidence." (PMID 28159730, 2017). "Thus, our results extend those of others which have focused on the functions of CD4+ TRM cells at the site of infection." (PMID 28419151, 2017). "To test these various interpretations, we cotransferred WT and GM-CSF−/− CD4+ T cells from M. tuberculosis-infected mice into sublethally irradiated recipients and monitored the ability of the T cell population to expand during infection." (PMID 29066547, 2017). "We next assessed the role of CD30 in the CD4 T-cell response during LCMV clone 13 infection." (PMID 28993768, 2017). "Although several reports have assessed the existence of alterations of CD4+ Foxp3+ regulatory T cells during T. cruzi infection, the role of this population during the acute phase of infection still remains unclear." (PMID 28938533, 2017). "Furthermore, CD4+ memory T cell responses were described in patients with blood stream infections and, in mice, adoptive transfer or induction of antigen-specific Th1 responses was protective against invasive infection." (PMID 28542586, 2017). "HIV infection famously depletes CD4+ T-helper (TH) cells, first quickly in the acute phase of infection, followed by a near-total recovery in numbers, and finally a steady decline over a number of years leaving the adaptive immune system at a tremendous disadvantage." (PMID 29255464, 2017). "Interestingly, Asl-deficient donor cells had reduced cell size and blasting compared with AslWT, suggesting that l-citrulline metabolism promotes a growth and accumulation advantage to mycobacterium-specific CD4+ T cells early during infection." (PMID 29201027, 2017). "The antiviral activity of GS-9620 in isolated macrophages, CD4+ T cells, and total PBMCs was assessed following infection with replication-competent strain HIV-1BaL or a single-cycle VSV G glycoprotein (VSV-G)-pseudotyped HIV-1 reporter virus encoding the luciferase protein (HIV-1VSV-G-LUC)." (PMID 27799218, 2017). "Thus, the significant pro-inflammatory response triggered by the infection of macrophages by Mtb was curtailed upon addition of lung CD4+ T-cells." (PMID 28880895, 2017). "Our data therefore identify two distinct populations of long-lived cells that are derived early following infection, likely via different mechanisms: a spleen IgM memory population that requires both CD4 T cell help and IL-21, and the CD4 T cell-independent BM ASCs." (PMID 28575114, 2017). "Progression of infection was monitored by the measurement of viral loads and CD4+ T cell numbers." (PMID 28465428, 2017). "In the mouse, we have shown marked infiltration of the local genital tract tissues with CD4+ T cells, which remain long after infection has resolved, as well as specific effector populations (neutrophils and perhaps others) that are required for antibody-mediated protection against C. muridarum." (PMID 28739831, 2017).
infection (continued). "Bacterial numbers in the organs even of those CD4+IFNγ-/- T cell recipients that succumbed to the infection were clearly reduced at the time of death compared to R. typhi-infected control mice, demonstrating bactericidal activity of CD4+IFNγ-/- T cells in vivo." (PMID 28222146, 2017). "Interestingly, on the other hand, NT women showed a significantly higher frequency of HCMV-specific CD4+ T cells with a IL-7Rpos phenotype than T women, both 1 month and 6–12 months after infection." (PMID 29112951, 2017). "Mice treated with anti-CD4 are markedly depleted, and the depletion regimen for neutrophils was highly effective in the genital tract, as neutrophils remained depleted throughout secondary infection." (PMID 28739831, 2017). "Similarly, CD4+ T cells with cytotoxic potential are specifically induced at the site of infection during influenza virus infection." (PMID 28289418, 2017). "However, proliferation of CD4 T cells from infected animals was recovered later on in the infection." (PMID 28114324, 2017). "The preferential infection of CCR6+ Th17 cells may be attributable to the higher expression of the viral receptors CD4, CXCR4, and α4β7 compared with CCR6− Th17 cells resulting in enhanced HIV envelope binding." (PMID 28509877, 2017). "This could have further been worsened by the concomitant use of intravenous steroids, oral steroids, and dexamethasone implant resulting in low CD4 counts and a disseminated form of infection." (PMID 28091937, 2017). "Interestingly, in controlled-infection granuloma-like structures from group A, the CD4+/CD8+ ratio was significantly higher than groups B and C." (PMID 27799331, 2017). "Besides a considerable expansion of CD4+ Foxp3+ Tregs in the mLN of infected mice, most prominent by day 10 post infection, we also detected increased frequencies of Tregs in the LP during the course of infection." (PMID 28938014, 2017). "Following Leishmania infection in the skin, innate macrophages, neutrophils and DCs are recruited to the site of inoculation, which can become infected and as a result, have specific and important roles in shaping CD4+ Th cell-dependent immune responses to infection." (PMID 29176972, 2017). "Based on the differences described in inflammatory cell recruitment, we hypothesized that differential chemokine activation during Opal524R infection accounts for the lower numbers of CD4+ T cells and NK cells recruited to the site of infection." (PMID 29138302, 2017). "Similarly, a decrease in the frequency of IL-10 positive CD4+ T-cells occurred in lung-derived T-cells at 24 and 48h post-infection." (PMID 28880895, 2017). "Thus, for both infections, the recruitment of approximately 60% of the lung CD4 T cells was due to the ongoing infection." (PMID 28436493, 2017). "Here, CD4+ T cells still protect a large percentage of animals with already established infection." (PMID 28770333, 2017). "Interestingly, a HDA Mabs infection of the GKO mice provoked CD4+ and CD8+ T cells capable of producing IL-4 and IL-10 in the pulmonary cavity." (PMID 28421165, 2017). "Furthermore, the frequency of GzmB+ CD4 cells correlated inversely with RNA load during acute HFRS, suggesting a potential impact of CD4 CTL responses in the control of infection." (PMID 28167943, 2017). "However, infection with L. infantum resulted in an increased expression of FoxP3, CD4+, TGF-β, IL-10, TNF-α and IFN-γ in the colon and jejunum and a reduction of CD8+ and IL-4." (PMID 27094260, 2017). "Here, we sought to determine whether the loss in HA-specific reactivity that occurs as a consequence of immunological memory could be reversed by selectively priming HA-specific CD4 T cells prior to secondary infection." (PMID 28493882, 2017). "From an adaptive immunity perspective, impaired CD8+ T-cell macrophage killing could drive a persistent pro-inflammatory cytokine and chemokine response, thus contributing to recruitment of CD4+ T cells to sites of infection and chronic inflammation." (PMID 28752134, 2017).
infection (continued). "The level of trans‐infection was then assessed using FACS analysis of p24‐positive CD4+ cells." (PMID 28923824, 2017). "All CD4+IFNγ-/- T cell recipients that received anti-IL-17A hardly lost weight upon R. typhi infection (left), showed a very weak temporary clinical score peaking on day 12 post infection (middle) and survived the infection (right)." (PMID 28222146, 2017). "Infection with dimorphic or opportunistic fungi induces calnexin-specific CD4+ T cells." (PMID 28344577, 2017). "Homing of CD4+ T-cells to the gut during the acute phase of infection in this model may, as in humans, trigger longer preservation of gut-associated CD4+ T-cell compartment, leading to delayed pathogenesis." (PMID 28579989, 2017). "Reduction in Ka/Ks for env genes of LTNP might result in significantly slower infection of CD4+ T cells compared with RP." (PMID 28663742, 2017). "Furthermore, it was observed that quality of immune response to HBV and clearance of infection was dependent on the viral inoculum size and CD4+ T cell priming." (PMID 28450868, 2017). "The protection provided by leishmanization is essentially T cell-mediated, whereby IFN-γ-producing CD4+ T cells are recruited to dermal sites of infection where they perform effector functions, including the promotion of microbicidal mechanisms in infected macrophages." (PMID 29167671, 2017). "Costimulatory signals provided by antigen presenting cells such as macrophages and DCs are critical for full activation of naïve antigen-specific CD4 T cells and promote their rapid expansion into cytokine-producing effector cells, which exert their antimicrobial functions at the site of infection." (PMID 28767735, 2017). "We reasoned that since eSF could both trans-infect and induce an increased state of permissivity in CD4+ T cells, they should be more effective than DCs at enhancing infection." (PMID 28207890, 2017). "In this context, the costimulation with CD8+ T cells and IL-2 signaling occurring few days after initial priming may drive the efficient transition of these CD4+ effectors to memory cells, thus ensuring a long-lasting protection from secondary infections." (PMID 28289418, 2017). "Considering that GRAIL is an inducer of impaired CD4 T cell proliferation during in vitro and in vivo tolerance, as well as being involved in CD4 T cell dysfunction during infection, we aimed to assess its expression in spleen cells from control and infected animals by real time PCR." (PMID 28114324, 2017). "To investigate whether the cross-protection induced by the PC-vaccine was mediated by CD8+ CTLs, we repeated the vaccination/infection experiments using CD8+ or CD4+ cell-depleted mice." (PMID 28322289, 2017). "We hypothesized that immunizing with HA peptides prior to the secondary infection would lead to a corresponding increase in HA-specific memory CD4 T cells with the potential to become Tfh." (PMID 28493882, 2017). "However, animal M4 has an extremely high CD4 count throughout the infection; and its set point CD4 count remains higher than 700 cells/μL while the maximum set point CD4 count of all other animals in the morphine group is 42 cells/μL." (PMID 27668463, 2016). "Additionally, both splenic and mesenteric CD4+ T cells had a high expression level of PD-1, even 8 weeks post-infection." (PMID 27792733, 2016). "Furthermore, we provide evidence that the increased levels of CD4 T cell infection were likely a consequence of bacteria-induced enhancement of CCR5 expression on CD4 T cells through indirect mechanisms." (PMID 26762145, 2016). "In response to L. monocytogenes infection, we detected reduced accumulation of CD4+ T cells responding to listeria-antigen with the up-regulation of CD40L, and in competitive transfer experiments, IRF4−/− CD4+ T cells were outnumbered by WT CD4+ T cells following infection or peptide immunization." (PMID 27762344, 2016).
infection (continued). "The results from these experiments do not support a proposed hypothesis that Opa proteins would inhibit CD4+ T cell proliferation when part of whole bacteria (as would be the case during infection) or contained within an OMV vaccine." (PMID 27111850, 2016). "Besides, the mortality in C57BL/6 mice after peroral infection appears to be due to severe necrosis of the small intestine, which has been shown to be CD4+ T cell-dependent and IFN-γ mediated." (PMID 28066269, 2016). "Additionally, the presence of cross-reactive memory CD4 T cells has been correlated with less severe disease following heterosubtypic infection in humans." (PMID 27148257, 2016). "We assessed the distribution of body size phenotypes overall, and according to antiretroviral therapy (ART), diagnosed duration of the infection and CD4 count in a sample of HIV infected people recruited across primary care facilities in the Western Cape Province, South Africa." (PMID 27271659, 2016). "Furthermore, MDV preferentially targets CD4+ T cell subsets and infection results in viral latency and immune evasion." (PMID 27894330, 2016). "The latent reservoir is also rapidly established during acute infection, supporting the notion that direct infection of resting CD4 T cells may also contribute to the latent reservoir." (PMID 26728316, 2016). "Notably, CD4+ T cells constituted a significantly higher fraction of the IL-10+ cells in the liver during the early stages of secondary compared with primary infection." (PMID 27630165, 2016). "Infection with La or Lb induced an increase in CD4+ T-cells in DLN; however, the number of CD4+ T-cells was greater in the Lb infection and displayed a Th1 immune phenotype, since IFNγ-producing CD4+ T-cells were only observed in the infection with Lb and not during La infection." (PMID 27073297, 2016). "However, CD4+ T-cells are required for generation of immune memory, as mice depleted of CD4+ T-cells prior to a primary infection or continuously depleted are unable to mount an effective memory immune response." (PMID 27242785, 2016). "The CD4+ T cell response to the MCMV m09133-147 epitope (here referred to as m09) was described as inflationary with 0.11–0.21% of the peripheral CD4+ T cell population producing IFNγ in response to m09 stimulation in persistently infected animals (days 40–100 post-infection)." (PMID 27861512, 2016). "The DC-SIGN mediated transfer of HIV to target cells involves binding of the virus to the DC-SIGN receptor, a process that occurs through interactions between high-mannose glycans on the surface of the envelope glycoprotein with DC-SIGN, followed by transfer to CD4+ target cells for infection." (PMID 27783038, 2016). "Indeed young MSM, with high CD4+ T-cell counts at the time of diagnosis, made up this cluster, which suggests recent infection." (PMID 28002469, 2016). "Given that we saw an increase in lung CD4+ Th1 cells following infection with T. muris, we wanted to test whether these cells were necessary for protection against papain-induced AAI." (PMID 26644379, 2016). "Consequently, the effect of anti–IL-10R administration on splenic Ag-experienced CD4+ T cell numbers was quantitatively higher during secondary infection compared with primary infection." (PMID 27630165, 2016). "During infection, IL-22 is secreted by CD4-positive cells in an IL-23-dependent fashion." (PMID 27650379, 2016). "Thus, determining the role of vaccine induced CD4 CTL in protection against infections is the next step in this area of intense research." (PMID 27014272, 2016). "However, a trend for an increase in Eomes expression in CD38+ CD4+ T cells following infection was observed." (PMID 27662621, 2016). "As a mechanism of resistance by IFNγ to the infection, it is generally believed that after infection, activation of CD4+ T cells by mycobacterial antigens results in clonal expansion and the production of IFNγ, which activates macrophages resulting in their becoming mycobactericidal." (PMID 26999357, 2016).